PVR (PVR cell adhesion molecule)
Diseases named in the same sentence as PVR in open-access papers (continued):
Sharing a sentence is not in itself a finding about the gene and the disease.
infection (44 papers, 2007 to 2025). The state of being infected such as from the introduction of a foreign agent such as serum, vaccine, antigenic substance or organism. "Consistent with the RT-qPCR results, P4 and P15 upregulated PVR/CD155 cell surface protein expression at 3 days post-infection (dpi)." (PMID 33897679, 2021). "For example, poliovirus uses poliovirus receptor (PVR) as the entry receptor, and mice transgenic for this human receptor become permissive to infection." (PMID 30914507, 2019). "Future studies using longitudinally linked viruses are needed to determine whether the capacity of Vpu to downmodulate NTB-A and PVR upon IFN treatment varies during the course of infection." (PMID 31213558, 2019). "However, studies in transgenic animals expressing the poliovirus receptor (PVR) suggest that other pathways are crucial for protection from infection in vivo." (PMID 26437794, 2015). "While P4- and P15-mediated PVR/CD155 upregulation was already evident at the mRNA level at 48 hpi, the increased PVR/CD155 protein level could only be observed after 3 days of P14 infection, suggesting that additional posttranslational events may be involved in the regulation of this ligand." (PMID 33897679, 2021). "For this reason, we used two different methods: (i) real-time PCR, which detects the viral DNA in an active infection, and (ii) a Western blot assay with viral antigen to screen for PCMV/PVR antibodies, indicating previous exposures and latent virus." (PMID 36609605, 2023). "This supports the hypothesis that the PVR CD155 is necessary for PV infection, although not the sole determinant of tissue tropism, and productive infection." (PMID 31354645, 2019). "Moreover, PVR’s role is non-redundant and cells lacking PVR are completely refractory to infection." (PMID 33499355, 2021). "While double KO of both PVR and PVRL2 further reduced viral replication, it failed to confer MDBK cells with complete resistance to infection." (PMID 38400072, 2024). "PVR (CD155) and Nectin-2 (CD112), ligands for DNAM-1, were highly expressed but not modulated by infection." (PMID 36341337, 2022). "No significant change in ULBP1 or PVR surface expression was detected and a slight increase in ULBP3 levels during infection with both strains was noticed." (PMID 28819195, 2017). "Like MYXV, infection with vMyx-M153KO did not affect expression of other NK ligands including HLA–E, MICA/B, ULBP1–3, and PVR (not shown)." (PMID 23762498, 2013).
hematologic cancers (3 papers, 2022 to 2024). "Previous studies have reported the prognostic implications of PVR expression in various solid and hematological cancer patients." (PMID 35625835, 2022). "Meanwhile, TIGIT recognizes poliovirus receptor (PVR or CD155), Nectin-2 (CD112), or Nectin-3 overexpressed in hematologic cancers." (PMID 35990652, 2022).
neurological disease (1 paper, 2025). "Also, 59 unique proteins were associated with AD, and 10 of them (17%) showed an association with AD and an additional neurological disease (CTF1, NSF and PRSS53 with PD; SIGLEC9 with ALS; CR1, CTSH, PARP1 and PVR with MS; LRRC37A2 with both PD and ALS; and IDUA with PD, ALS and MS)." (PMID 40037332, 2025).
PVR also shares sentences with these, for which no sentence is quoted: lymph node metastasis (7 papers); sarcoma (7); head and neck squamous cell carcinoma (6); metastatic melanoma (6); cholangiocarcinoma (5); COVID-19 (5); malignant glioma (4); pancreatic ductal adenocarcinoma (4); Autoimmunity (3); brain tumor (3); breast tumors (3); esophageal squamous cell carcinoma (3); fibrosarcoma (3); gastric adenocarcinoma (3); head and neck cancer (3); lymphoma (3); rectal cancer (3); Sepsis (3); allergic disease (2); atherosclerosis (2); bladder tumor (2); brain cancer (2); cervical tumor (2); colitis (2); digestive system cancer (2); digestive system tumors (2); gastritis (2); HCMV infection (2); Hypertension (2); intraepithelial neoplasia (2).
A further 74 diseases each share a sentence with PVR in 2 papers or fewer.